C9orf72 (C9orf72-SMCR8 complex subunit)
Diseases named in the same sentence as C9orf72 in open-access papers (continued):
Sharing a sentence is not in itself a finding about the gene and the disease.
Alzheimer disease (47 papers, 2012 to 2026). A progressive, neurodegenerative disease characterized by loss of function and death of nerve cells in several areas of the brain leading to loss of cognitive function such as memory and language. "We find parallel neuroinflammatory mechanisms, dependent on TYK2 - a potential disease-modifying target - for TDP-43-associated Alzheimer's disease and C9ORF72-ALS." (PMID 41832177, 2026). "Moreover, the detection of repeat expansion in C9orf72 has been also associated with Parkinsonism, Huntington phenocopies, Alzheimer’s disease, corticobasal degeneration, and psychosis." (PMID 32455692, 2020). "Considering the long prodromal DPR accumulation accompanied by subtle brain atrophy in C9orf72 patients, mutation carriers may require very early treatment as proposed for Alzheimer's disease." (PMID 28351931, 2017). "We describe an additional case and report results of a genetic association analysis in a very large Alzheimer disease (AD) dataset and a bioinformatic analysis demonstrating altered expression of C9ORF72 in patients with other neurological conditions and expression patterns in the brain." (PMID 23060854, 2012). "While hallucinations in individuals with FTLD are not rare, and occur more frequently in certain FTLD subtypes (e.g., C9orf72 carriers), they are less common than in Lewy body disease or Alzheimer's disease." (PMID 37471695, 2023). "It is therefore conceivable that the Aβ peptide and the C9orf72-derived G-quadruplex RNA play equivalent roles in heme sequestration and activation in Alzheimer's Disease and in Familial ALS and FTD, respectively." (PMID 25207541, 2014). "Curiously, the ability of C9orf72 DNA and transcripts to bind and activate heme mirror similar properties that have been reported for the Aβ peptide and its oligomers in Alzheimer's disease neurons." (PMID 25207541, 2014). "Indeed, hnRNP K cytoplasmic mislocalization has been reported in FTLD, Alzheimer’s disease, and C9orf72-related ALS, suggesting a link to TDP-43 functional impairment in these neurodegenerative diseases." (PMID 40778857, 2025). "Therefore, we hypothesised that genetically reducing Keap1 levels to constitutively boost CncC activity could benefit C9orf72 phenotypes as has been seen in a Drosophila model of Alzheimer’s disease." (PMID 38906677, 2024). "To determine whether expanded GGGGCC repeat sense foci are a characteristic and specific feature of C9FTLD, we performed RNA FISH on 8 C9FTLD cases, 7 FTLD-TDP cases without C9orf72 mutation, 3 Alzheimer’s disease cases and 10 age-matched controls." (PMID 24170096, 2013). "Protective relationships were similarly observed across proteinopathies, including FTD TDP-43 (C9orf72 and GRN), FTD tauopathy (MAPT), and Alzheimer’s disease, suggesting transdiagnostic relevance." (PMID 39816189, 2025). "These include human diseases (autism, schizophrenia, genetic-C9orf72 ALS, Alzheimer’s disease), in vivo models of epilepsy, and prion diseases." (PMID 35327657, 2022). "Disruption of the nucleocytoplasmic RAN gradient has been observed in neurodegenerative diseases, such as C9ORF72-ALS, Huntington’s disease, and Alzheimer’s disease." (PMID 33362237, 2020). "PCR-based assessments of the C9orf72 hexanucleotide repeat expansion in all study samples (including 82 FTD, 37 Alzheimer’s disease (AD), and 16 other neurodegenerative/dementia disorder cases) were performed." (PMID 30550541, 2018). "In particular, the patients carrying C9orf72 repeat expansion were younger at onset, at first clinical observation, and at diagnosis and exhibited higher odds of bulbar onset, FTD diagnosis, and family history of ALS, FTD, and Alzheimer’s disease." (PMID 32455692, 2020). "It is therefore conceivable that C9orf72 RNA G-quadruplex tangles play roles in sequestering intracellular heme and promoting oxidative damage in ALS and FTD analogous to those proposed for Aβ peptide and its tangles in Alzheimer's Disease." (PMID 25207541, 2014).
Alzheimer disease (continued). "In addition, dysregulated lncRNAs were also found in neurodegenerative diseases in human, such as lncRNA BACE1-AS and BC200 (Alzheimer’s disease, AD), PINK1-AS (Parkinson’s disease), NEAT1 and MEG3 (Huntington’s disease), AS C9ORF72 (amyotrophic lateral sclerosis) and so on." (PMID 31316349, 2019).
motor neuron disease (40 papers, 2012 to 2026). "Among them, cluster #0 (motor neuron disease) was the largest, followed by #1 (neuron), #2 (small molecule), #5 (parent-of-origin effect), #6 (polyglutamine diseases), #7 (c9orf72 repeat expansion mutation) and #8(liquid-liquid phase separation)." (PMID 38628764, 2024). "The negative genetic interaction between defective autophagy and compromised nuclear pore function is not confined to HD, as both defects have been reported in other diseases, like motor neuron disease caused by C9orf72 mutations and tauopathy." (PMID 39209961, 2024). "All c9orf72 pathogenic variant carriers with a predominant bulbar ALS-MP had confirmed motor neuron disease." (PMID 35948443, 2022). "The exclusion of patients with ALS spectrum disorders, including primary lateral sclerosis, primary spinal muscular atrophy, and other motor neuron disease (N = 7) or patients with C9orf72 mutations (N = 10) only changed these results marginally." (PMID 36347843, 2022). "ALS is a motor neuron disease with a number of known genetic risk factors including C9orf72 repeat expansion." (PMID 34206848, 2021). "A hexanucleotide expansion in C9orf72 is the major genetic cause of inherited behavioural variant Frontotemporal dementia (bvFTD) and motor neurone disease (MND), although the pathological mechanism(s) underlying disease remains uncertain." (PMID 26538301, 2016). "Repeat expansions in different loci can also yield similar phenotypic features, making them difficult to distinguish clinically: repeat expansions in at least ten spinocerebellar ataxia genes frequently present as adult-onset ataxia, and those in C9orf72 and AR can both cause motor neuron disease." (PMID 35182509, 2022). "Among its clinical variants, the behavioral variant (bvFTD) is the most frequently inherited, often associated with mutations in MAPT, GRN, and C9ORF72, the latter being the most prevalent genetic cause of FTD and FTD-motor neuron disease (FTD-MND)." (PMID 41500252, 2026). "For FTD subtypes, C9orf72 showed a colocalization signal for a shared causal variant between ALS and the motor neuron disease subtype of FTD (mndFTD, PPH4 = 93%)." (PMID 34873335, 2021). "In fact, despite being the most frequent genetic cause of motor neuron disease, C9orf72 mutations do not explain the whole spectrum of pathological phenotypes observable in ALS." (PMID 35774867, 2022). "The most common genetic cause of FTD, the GGGGCC hexanucleotide repeat mutation in C9orf72,17 can present with symptoms consistent with a bv‐FTD or motor neuron disease (or both), as well as psychiatric symptoms that may predate cognitive symptoms by up to two decades." (PMID 36807325, 2023). "While neuron and glia specific C9orf72 ablation or intracerebral mRNA knockdown does not seem to cause motor neuron disease in mouse models, our data and recent data by others consistently demonstrate that whole body C9orf72 deficiency produces severe immune dysregulation in mice." (PMID 27193190, 2016). "Therefore, despite the numerous evidences that C9ORF72 loss of function does not cause motor neuron disease without additional hits, targeting C9ORF72 haploinsufficiency early on in the disease course might be of strong therapeutic interest in C9ALS." (PMID 37138765, 2023). "All C9orf72 cases presented with the clinical syndrome of bvFTD, with psychotic symptoms present in 4 of the cases, and none with concomitant motor neuron disease." (PMID 30988363, 2019). "Although these results still need to be confirmed in a larger cohort of CBS and/or CBD patients, these data suggest that in the presence of a family history and/or motor neuron disease features, patients with CBS or clinical PSP should be screened for the C9orf72 repeat expansion." (PMID 25308964, 2015).
motor neuron disease (continued). "Although 21.7% of c9orf72 pathogenic variant carriers with a predominant mixed/ALS-MP had confirmed motor neuron disease, in none of the patients with a GRN or MAPT pathogenic variant, motor neuron disease was diagnosed." (PMID 35948443, 2022). "In fact, C9orf72-null mice developed normally and aged mice do not suffer from motor neuron disease, but have other phenotypes that may well be relevant to C9orf72’s recently deciphered roles in membrane trafficking and autophagy." (PMID 27774051, 2016). "Finally, a recent RNA-Seq study comparing C9 FTLD and FTLD/motor neuron disease patients with unaffected control individuals reported a highly significant decrease in C9orf72 RNA levels in C9 FTLD samples; however, this data showed no significant change in SMCR8 or WDR41 RNA expression." (PMID 32678027, 2020).
Cognitive impairment (38 papers, 2012 to 2025). Abnormal cognition is characterized by deficits in thinking, reasoning, or remembering. "Advanced stages of ALS/FTD, including in C9orf72 repeat expansion patients, are associated with synaptic loss, where the extent of loss correlates with the clinical severity of cognitive impairments." (PMID 35876881, 2022). "Intriguingly, none of the patients with ALS carrying NEK1 LoF variants described up to date had cognitive impairment, except for one case, whereas C9orf72 association to ALS-FTD is well known." (PMID 35495032, 2022). "C9ORF72 is also highly expressed in microglia, and recent work has determined that loss of C9ORF72 exacerbates microglial synaptic pruning activity in the cortex, which correlates with cognitive impairments." (PMID 34975412, 2021). "Our C9-ALS/FTD zebrafish model is the first to recapitulate the motor deficits, cognitive impairment, muscle atrophy, motor neuron loss and mortality in early adulthood observed in human C9orf72-ALS/FTD." (PMID 30454072, 2018). "Recently, a hexanucleotide expansion in the C9orf72 locus was genotyped both in fALS and sALS patients who more frequently showed a pronounced cognitive impairment compared to those carrying other genetic mutations." (PMID 30210287, 2018). "Our findings suggest that poly-GA-induced protein sequestration and regional microglia activation may be responsible for the prodromal cognitive deficits observed prior to complete ALS/FTD symptoms in C9orf72 mutation carriers." (PMID 28409281, 2017). "It should be noted that one patient (Patient 1684) with FTD had a concomitant C9orf72 repeat expansion and a family history of cognitive impairment." (PMID 39766833, 2024). "According to our findings, C9orf72 carriers will play a special role in this biomarker work-up as their oculomotor and cognitive impairments probably develop early in life already." (PMID 33709219, 2021). "Two mismatch cases had an underlying genetic mutation, both of which were a C9orf72 hexanucleotide repeat expansion (30%), compared to five genetic mutations (four C9orf72 and one NEK1 mutation) in the 11 comparison cases with cognitive deficits (45%)." (PMID 31386770, 2020). "Age at symptom onset, BMI, bulbar involvement, cognitive impairment, C9orf72 genotype status, respiratory insufficiency, “definite ALS” by the El Escorial criteria, and functional disability are the most commonly cited determinants of poor prognosis in ALS." (PMID 30941088, 2019). "Furthermore, hexanucleotide repeat expansions were shown to enhance the phenotypic features, such as cognitive defects, activated astroglia and hippocampal neurodegeneration upon C9orf72 depletion in double-transgenic mice." (PMID 39316747, 2024). "Carriers of C9orf72 mutations have a significantly higher risk of developing cognitive impairment (40–50%) than patients lacking this mutation (8–9%)." (PMID 34441299, 2021). "As C9orf72 expansions in human ALS cause a spectrum of both motor and cognitive deficits, we examined whether normal zebrafish behaviour was affected in 2.2–7 zebrafish at 5 dpf." (PMID 30454072, 2018). "Indeed, C9Pos patients with larger expansions had a more severe cognitive impairment, thereby supporting the emerging hypothesis that C9orf72 HRE size may be a modifier factor of phenotype along the ALS-FTD clinical spectrum." (PMID 36308529, 2023). "Jiang and colleagues demonstrated that a single, intraventricular administration of a C9orf72-ASO that mediates RNase H degradation could reduce RNA foci and dipeptide aggregates and improve the behavioral and cognitive deficits associated with the C9orf72 repeat expansion in the C9-450 mouse model." (PMID 31500113, 2019). "Relatively isolated agraphia in two cases with C9orf72 repeat expansions is a strong motivation to provide detailed and sophisticated oral and written language assessments that can be used to more precisely characterize early cognitive deficits in these heterogeneous conditions." (PMID 30550541, 2018).
Cognitive impairment (continued). "An increase in A8RNA levels and a corresponding decrease in C9orf72 transcription, coupled with reduced PAPOLA activity, could contribute to cognitive deficits after aSAH by hindering the activation of stress response pathways." (PMID 39726593, 2024). "In our study, none of the NEK1 LoF carriers had cognitive impairment; moreover, we found three patients carrying a NEK1 likely benign missense variant that presented also with FTD, but all of them carried also the C9orf72 expansion." (PMID 35495032, 2022). "As C9orf72-ALS lies on a genetic and clinical spectrum with FTD, we also tested whether expression of GR50 correlated with a measurable cognitive impairment." (PMID 35379876, 2022). "Mild neurodegeneration and cognitive impairment have been reported in some gain-of-toxic-function GGGGCC repeat C9orf72 BAC-transgenic mice but not others, while loss-of-function C9orf72 knockout mice exhibit an immunological rather than neuronal phenotype." (PMID 27768524, 2018). "The spectrum of involvement in families carrying C9orf72 gene expansions differs significantly from typical ALS based on purely behavioral symptomatology (bvFTD), i.e., without demonstrable motor neuron involvement up to a combination of ALS and cognitive impairment." (PMID 34441299, 2021).
Huntington disease (37 papers, 2015 to 2025). Huntington disease (HD) is a rare neurodegenerative disorder of the central nervous system characterized by unwanted choreatic movements, behavioral and psychiatric disturbances and dementia. "It is noteworthy that in certain European populations, the hexanucleotide repeat expansion in C9orf72 has been identified as the most prevalent cause of phenocopies resembling Huntington’s disease (HD)." (PMID 38356886, 2024). "Although distinct from tandem repeat expansions such as HTT-CAG in Huntington’s disease or C9orf72-GGGGCC in ALS/FTD, all forms of repeat-associated challenge replication fidelity, promote secondary structure formation, and interfere with recombination accuracy." (PMID 41282088, 2025). "There are limitations with this technology in that large duplications and structural variations cannot be read by these techniques, nor can triplicate repeat disorders such as the CAG (cytosine, adenine, guanine) repeat in Huntington disease and disorders related to the C9orf72 mutation." (PMID 36807325, 2023). "These HD phenocopies include neurodegenerative diseases caused by repeat expansions in the C9orf72 gene, spinocerebellar ataxia (SCA) 17, Huntington disease-like 2 (HDL2), dentatorubropallidoluysian atrophy (DRPLA), neuroferritinopathy, familial prion disease (e.g. Huntington disease-like 1 [HDL1])." (PMID 32832197, 2020). "A pathogenic GGGCC (G4C2) hexanucleotide expansion in intron 1 of the C9orf72 gene is the most common mutation associated with both ALS and FTD and is implicated in Huntington's disease." (PMID 30564290, 2018). "For example, C9orf72 expansions can present as either FTD or ALS even within the same family; and one in three patients carrying the repeat expansion in C9orf72 shows an atypical presentation at onset such as Alzheimer’s and Huntington disease (HD) among others." (PMID 39354197, 2024). "Like in presymptomatic Huntington’s disease and pre-ataxic Machado–Joseph disease individuals, the recording of eye movements in presymptomatic C9orf72 gene carriers may have the potential as a biological marker." (PMID 33709219, 2021). "The accumulation of RAN proteins has been found in the disease-relevant tissue of a growing number of repeat expansion disorders, including spinocerebellar ataxia type 8 (SCA8), Huntington’s disease (HD), C9orf72 ALS/FTD, and myotonic dystrophy type 1 and type 2." (PMID 31426500, 2019). "RAN translation appears to be a pathological mechanism in the hexanucleotide repeat expansion disorder C9orf72, the most common genetic mutation associated with ALS-FTD, and may also occur in the CAG repeat expansion disorder Huntington’s disease." (PMID 30808398, 2019). "Mitochondrial transport deficits are linked with several neurodegenerative disorders, such as Alzheimer’s and Huntington’s disease, hereditary spastic paraplegia, Charcot–Marie–Tooth disease, as well as ALS with SOD1, TARDBP, and FUS mutations, and ALS with hexanucleotide repeats in C9orf72." (PMID 38363426, 2024).